WNT3A (Wnt family member 3A)
Diseases named in the same sentence as WNT3A in open-access papers (continued):
Sharing a sentence is not in itself a finding about the gene and the disease.
melanoma (continued). "Despite not affecting total mitochondrial content, we did find that WNT3A was capable of altering the mitochondrial membrane potential (ΔΨm) of PTENWT melanoma cells, using fluorescent probes." (PMID 28092677, 2017). "Indeed transient knockdown of PTEN in PTENWT melanoma cells reduced MFN1 expression, thereby antagonizing WNT3A-mediated increased MFN1 expression and of note PTEN depletion appears to reduce MFN1 expression in these cells." (PMID 28092677, 2017). "We treated a panel of melanoma cell lines for 4–6 weeks in the continued presence of 2 μM vemurafenib (BRAFi) and in the presence or absence of WNT3A." (PMID 24733413, 2014). "To determine whether depletion of PKN1 can further activate β-catenin signaling elicited by WNT3A and BRAF inhibitor (BRAFi) in melanoma, we transfected A375 cells harboring BAR with siRNAs targeting PKN1 or control duplexes." (PMID 24114839, 2013). "Transfecting A2058 cells with WNT3A leads to a 5.2-fold enhancement of BAR-luciferase, which was inhibited by siRNA-mediated knockdown of WLS and VPS35 suggesting that WLS-dependent WNT secretion regulates WNT/β-catenin signalling in melanoma." (PMID 23129487, 2012). "Both Wnt1 and Wnt3a have been shown to activate RhoA, whereas the non-canonical Wnt5a promotes melanoma migration via RhoB." (PMID 19473496, 2009). "To validate loss of functionality at the PAK4 kinase domain, we evaluated whether B16 PAK4 KD cells had decreased phosphorylation of β-catenin S675 and reduced response to Wnt-3a stimulation, as we have previously observed in B16 PAK4 KO cells as well as in human melanoma PAK4 KO cells." (PMID 36588582, 2022). "Since we observed a close correlation between the Wnt3a-CM or PKF115–584 treatment and the expression of pigmentation related genes (DCT, TYR, TYRP1, MITF) in our SKMEL28 microarray data, we analyzed the TCGA melanoma RNAseq expression data concerning MLANA expression." (PMID 29454361, 2018). "As we were unable to detect increased mitochondrial networking in PTENMut melanoma cells in response to WNT/β-catenin signaling, we hypothesized that reduction of PTEN in PTENWT cells would block WNT3A-mediated mitochondrial fusion." (PMID 28092677, 2017). "However, this is not the case for PTENMut melanoma cells, which do not respond consistently to WNT3A-mediated metabolic reprogramming." (PMID 28092677, 2017). "Indeed, overexpression of Wnt3a reduced proliferation of human or mouse melanoma cells, and pharmacological activation of Wnt via treatment with Riluzole or a GSK3 inhibitor (LY2090314) inhibits melanoma cell growth." (PMID 27196929, 2016). "We did, however, find that WNT3A signaling could markedly alter the invasive properties of the melanoma cell panel in MatrigelTM, where PTENWT cells responded with significantly reduced invasive capacity and PTENMut lines with enhanced invasion in response to WNT3A-activated signaling." (PMID 28092677, 2017). "And lastly, secreted WNT5A (as opposed to WNT3A) has been shown to negatively regulate WNT/β-catenin signaling in several cancer types, including in a subgroup of melanoma patients exhibiting acquired resistance to BRAF-inhibition." (PMID 32238882, 2020). "In contrast, most of these peptides did not change in abundance in WNT3A-stimulated A375 cells (red dots), suggesting that WNT3A does not broadly inhibit the kinase activity of GSK3 in melanoma cells." (PMID 24114839, 2013). "To validate our siRNA screening findings, we treated A375 human melanoma cells with five distinct siRNAs targeting PKN1 and then assayed the expression of the β-catenin-activated reporter in the presence or absence of exogenous WNT3A." (PMID 24114839, 2013).
hepatocellular carcinoma (26 papers, 2011 to 2025). A malignant tumor that arises from hepatocytes. "WNT3A regulates the cell cycle and metastasis and acts as a prognostic marker of hepatocellular carcinoma." (PMID 34287269, 2021). "Overexpression of miR-195 can target Wnt3a, inhibit proliferation of hepatocellular carcinoma cells, and promote apoptosis." (PMID 30581678, 2018). "Wnt3a can enhance hypoxia-induced epithelial-mesenchymal transition (EMT) in hepatocellular carcinoma (HCC)." (PMID 26369691, 2015). "Overactivation of Wnt signaling in hepatocellular carcinoma cell lines identified WISP2 as a downstream target of Wnt3A." (PMID 24637805, 2014). "Co-expression of FZC18 and Wnt3a in non permeabilized AT3F1S315 mouse hepatoma cells followed by confocal microscopy analysis revealed that both proteins colocalized at the cell surface, highlighting cell contacts." (PMID 22303445, 2012). "We found that β-catenin levels were significantly increased in the nuclear fraction of core-expression hepatoma cells, peaked at 4 hrs after Wnt3A stimulation, corresponding to a simultaneous decrease of β-catenin protein level in the cytoplasmic fraction." (PMID 22110662, 2011). "Additionally, WNT3A overexpression in esophageal squamous cell carcinoma and hepatocellular carcinoma indicates poor prognosis." (PMID 34565373, 2021). "Additionally, hepatocellular carcinoma is rich in blood vessel‐ and tumour cell‐derived Wnt3a, which easily enters the circulating blood system." (PMID 31111621, 2019). "Other researchers have shown that the hypoxia-induced EMT may be enhanced by the addition of recombinant canonical Wnt3a, whereas it is repressed by β-catenin siRNA in hepatocellular carcinoma." (PMID 25396735, 2014). "Our data reveal that high expression of Wnt3a is significantly correlated with lymph node metastasis and advanced clinical stages, which is consistent with the results of previous studies in other human malignancies including hepatocellular carcinoma and lung adenocarcinoma." (PMID 31111621, 2019). "Another scFv antibody, HS20, inhibits the proliferation of hepatocellular carcinoma (HCC) cells in vitro and in vivo by binding to the HS chains of glypican-3 to block Wnt3a/β-catenin signaling, which recognizes HS structures containing IdoA2S and GlcNS6S." (PMID 36265583, 2022). "Linc00662 promotes hepatocellular carcinoma (HCC) progression and M2 macrophage polarization by upregulating WNT3A expression and secretion through competitive endogenous RNA (ceRNA) mechanism." (PMID 35071016, 2021). "This nuclear translocation effect was further strengthened when core and Wnt3A were co-expressed, Similar results for nuclear translocation of β-catenin induced by HCV core were obtained in hepatoma cell lines Huh7 cells using immunostaining assay." (PMID 22110662, 2011). "Additionally, it plays a role in promoting hepatocellular carcinoma via the miR-203b/VEGFA axis and contributes to the progression of bladder cancer by modulating the Wnt3a/β-Catenin signaling pathway." (PMID 38279317, 2024). "Many in vitro and in vivo studies show that in different tumor types, such as colorectal, lung, breast, or hepatocellular cancer, specific WNTs, including WNT1, WNT2, WNT3A, WNT6, WNT8B, WNT7B, and WNT16B, can activate canonical Wnt signaling and support tumor proliferation." (PMID 36982422, 2023). "Like free hGC33, nanodrug surface-modified hGC33 inhibited the proliferation of hepatoma cells not only by blocking Wnt-induced signal transduction in HepG2 and Huh-7 cells of expressing GPC3, but also by inhibiting Wnt3a-induced β-catenin and YAP signal transduction." (PMID 33242103, 2020). "There was a dramatic increase in the expression level of c-Myc and cyclin D1 (data not shown) after co-expression of Wnt3A and core in hepatoma cells." (PMID 22110662, 2011). "Meanwhile, another study on hepatocellular carcinoma showed that recombinant Wnt3a could not induce Huh-7 or HepG2 cells to undergo EMT in normoxia." (PMID 25499541, 2014).
lung carcinoma (25 papers, 2008 to 2026). "Interestingly, fine particulate matter (PM2.5) also increases the risk of lung cancer by promoting WNT3a levels in secreted exosomes and subsequent activation of the canonical WNT pathway." (PMID 37486552, 2023). "For example, A549 lung cancer cells exposed to fine particulate matter secrete exosomes with high levels of Wnt3a, and these exosomes stimulate A549 cell proliferation in vitro and in vivo, via Wnt3a/β-catenin pathway." (PMID 37915578, 2023). "In conclusion, these findings provide a theoretical basis for using WNT3a as a drug target to treat lung cancer." (PMID 37486552, 2023). "Other researchers reported that PM2.5 upregulated Wnt3a/β‐catenin pathway and IL-17a signal pathway or reduced the levels of 15-lipoxygenases, which influenced the progression of lung cancer." (PMID 36496421, 2022). "Addition of exosomes from PM2.5-treated lung cancer cells promoted the growth of lung cancer cells through activation of the Wnt3a/β-catenin pathway." (PMID 35448437, 2022). "Ninj1-mediated Wnt/β-catenin signaling is further enhanced by the addition of exogenous Wnt3a, a Wnt ligand that activates the canonical Wnt signaling pathway and promotes lung cancer progression." (PMID 35395804, 2022). "Upregulation of CYP4B1 during AT2-to-AT1 TD is affected by a specific ligand Wnt3a, that plays an important role in in lung cancer." (PMID 31492143, 2019). "In conclusion, we think that the combined use of h-Prune and Wnt3a can be of impact for lung cancer diagnosis improving sensitivity and specificity." (PMID 25026278, 2014). "As expected, serum concentrations of Wnt3a in lung cancer patients was higher than in healthy controls (P= 0.03)." (PMID 25026278, 2014). "For this reason, the serum levels of Wnt3a in lung cancer patients (n = 24) and healthy controls (n = 10) were assessed using ELISA assays." (PMID 25026278, 2014). "Here we report that Ror2 also positively modulates Wnt3a-activated canonical signaling in a lung carcinoma, H441 cell line." (PMID 18215320, 2008). "Additionally, Wnt3A-enriched exosomes secreted by lung cancer cells after PM2.5 exposure activated the Wnt/β-catenin signaling pathway, promoting cell proliferation and xenograft tumor growth." (PMID 41545904, 2026). "Furthermore, PM2.5-treated lung cancer cells release exosomes enriched in Wnt3a, which activate β-catenin signaling in recipient cells and drive proliferation and tumor progression in a Wnt3a-dependent manner." (PMID 41345682, 2025). "Overall, the results showed that the use of Wnt3a as serum lung tumor marker had good specificity but poor sensitivity, in contrast, the sensitivity and the specificity of h-Prune detection alone is sufficient to identify lung cancer affected patients." (PMID 25026278, 2014). "Finally, we evaluated the value of h-Prune and Wnt3a as tumour markers investigating their protein levels in peripheral blood of lung cancer patients." (PMID 25026278, 2014). "Further studies are needed to investigate the role of Wnt3a in lung cancer." (PMID 23815780, 2013). "Ginkgo biloba exocarp extracts (GBEE) can suppress Wnt3a and β-catenin protein expression and VEGF mRNA levels in Lewis lung cancer (LLC) cells." (PMID 34976156, 2022). "It is also demonstrated that gamma-tubulin complex protein-5 (GPC5) competitively bound Wnt3a to inactivate the Wnt/β-catenin signaling pathway and inhibited the EMT of lung cancer cells." (PMID 28798691, 2017). "As shown, several well‐known oncogenes were co‐expressed with circRNA, such as Wnt3A, CDK1, and BUB1, indicating these circRNA might participate in the pathological process of lung cancer." (PMID 29632808, 2018). "We thus believe that great importance should be given by the combination of both h-Prune and Wnt3a expression analyses in the serum in those patients with early stage of NSCLC, this approach might improve lung cancer diagnosis." (PMID 25026278, 2014). "First, we find that PRC1 is not induced by Wnt3a in lung cancer cell lines." (PMID 29435157, 2018).
lung carcinoma (continued). "The expression level of β-catenin in lung cancer cells with cir-ITCH hyperexpression was further confirmed by western blotting analysis, and it was discovered that there was an obvious decrease in β-catenin levels, while no change in Wnt3a expression was shown." (PMID 27642589, 2016).
gastric cancer (23 papers, 2015 to 2024). A primary or metastatic malignant neoplasm involving the stomach. "Gastric cancer patient-derived organoids incubated in Wnt3a-depletion medium were more susceptible to dose-dependent inhibition of cell viability by trastuzumab than those incubated in complete medium." (PMID 37773114, 2023). "High expression of WNT3A is closely associated with neural infiltration in gastric cancer patients and may be caused by activation of matrix metalloproteinases (MMPs) downstream of the Wnt/β-catenin pathway." (PMID 38952556, 2024). "miR-132–3p and miR-140–5p can reduce the expression of WNT1 and inhibit gastric cancer cell proliferation and invasion; miR-491–5p can target and silence Wnt3a, inhibit the proliferation of gastric cancer cells and induce apoptosis." (PMID 38952556, 2024). "It has been reported that FOXI1 decreases gastric cancer cell proliferation through the posttranscriptional destabilization of WNT3A mRNA." (PMID 37011861, 2023). "Gastric cancer organoid cells were incubated with complete medium and Wnt3a-depletion medium, and their resistance to trastuzumab was compared." (PMID 37773114, 2023). "Knockdown of PDIA6 reduced protein expression of Wnt3a and β-catenin in gastric cancer cells, and activation of Wnt pathway through incubation with lithium chloride attenuated PDIA6 silencing-induced increase in chemosensitivity." (PMID 34781823, 2021). "In gastric cancer, Wnt3A and FZD6 mediated trastuzumab resistance by activating Wnt/β-catenin pathway." (PMID 33618667, 2021). "FOXI1-mediated miR-491-5p serves as a tumor repressor in gastric cancer via targeting Wnt3a/β-catenin pathway." (PMID 32808668, 2020). "The receptor for activated protein kinase C inhibits Wnt3a signaling by inhibiting the recruitment of Axin by Dvl2 and by stabilizing the β-catenin destruction complex and acts as a tumor suppressor in gastric cancer cells." (PMID 26369691, 2015). "When gastric cancer cells were incubated in Wnt3a-conditioned medium." (PMID 37773114, 2023). "Additionally gastric cancer cells incubated in Wnt3a-conditioned medium exhibit increased activity of Wnt signaling pathway and trastuzumab resistance." (PMID 37773114, 2023). "For example, exosomes that are rich in wnt3a and released from gastric carcinoma cells can be ingested by the peritoneal mesothelial cells, which results in the infiltration of peritoneal mesothelial cells and the invasion of gastric carcinoma cells." (PMID 34686196, 2021). "Meanwhile, downregulation or overexpression of IRF3 in human gastric carcinoma cell lines BGC-823 and HGC-27 did not affect the Wnt target or associated genes expression upon wnt3a treatment." (PMID 33188184, 2020). "In a study, curcumin suppressed the proliferation of gastric cancer (GC) cells by downregulating the target genes of the Wnt/β-catenin pathway, namely Wnt3a, LRP6, β-catenin, c-myc, and surviving." (PMID 39507759, 2024). "Therefore, we investigated whether the Wnt signaling pathway could be activated when parental gastric cancer cells were incubated in the Wnt3a-conditioned medium." (PMID 37773114, 2023). "Subsequently, a confirmation of the suppression of the Wnt/β-catenin signaling pathway by curcumin was provided, showing a decreased expression of Wnt3a, LRP6, phospho-LRP6 and phospho-β-catenin, as well as C-myc, and surviving in gastric carcinoma xenografts." (PMID 37376060, 2023). "The high expression of LINC01606 in gastric cancer (GC) liberates miR‐423‐5p bound to Wnt3a through a competitive endogenous RNA (ceRNA) mechanism, thereby upregulating Wnt3a expression and inhibiting the Wnt/β‐catenin pathway to promote gastric cancer cell metastasis." (PMID 33174687, 2020). "In gastric cancer cells, Wtn3a stimulation promotes SMYD3 transcript expression, through the direct recruitment of β-catenin/TCF4 complex in Wnt3a-treated SGC7901 gastric cancer cells." (PMID 31935919, 2020).
gastric cancer (continued). "WNT3A/Wnt family member 3A Through the inhibition of WNT3A, miR-491 plays a role in the regulation of Wnt3a/β catenin signaling in gastric cancer, with its activation observed in the early phase of colitis-associated tumor development." (PMID 31752264, 2019). "Our results suggest that over-expression of Wnt3A and FZD6 activates the Wnt/β-catenin pathway in trastuzumab resistant gastric cancer cells, which is accompanied with EMT." (PMID 29986466, 2018). "As a procarcinogenic gene in gastric cancer tissues, WNT3A expression is nearly twice that in adjacent noncancerous tissues, not only promoting malignant proliferation of gastric cancer cells and inhibiting apoptosis but is also patient chemoresistance and gastric cancer neuroinvasion." (PMID 38952556, 2024). "However, it is worth noting that WNT3A mRNA is not detected in any of the seven gastric cancer cell lines." (PMID 38800305, 2024).
osteoporosis (22 papers, 2012 to 2025). A condition of reduced bone mass, with decreased cortical thickness and a decrease in the number and size of the trabeculae of cancellous bone (but normal chemical composition), resulting in increased fracture incidence. "Piezoelectric microvibration mitigates estrogen loss-induced osteoporosis and promotes piezo-type mechanosensitive ion channel component 1 (Piezo1), miR-29a, and Wnt family member 3a (Wnt3a) signaling in osteoblasts." (PMID 36831000, 2023). "Interestingly, low levels of β‐catenin as a downstream effector of Wnt3a lead to enhanced OC differentiation and cause osteoporosis." (PMID 26416438, 2015). "miRNA-9-5p promotes the occurrence and development of osteoporosis by targeting Wnt3a, inhibiting osteogenesis, and promoting adipogenesis." (PMID 35845940, 2022). "T2DM inhibits OB differentiation and bone formation by inhibiting the Wnt3a/β-catenin pathway, leading to the degradation of the bone morphological structure and the initiation of osteoporosis." (PMID 34688315, 2021). "Therefore, improving the activation of Wnt3a/β-catenin was an important target in anti-osteoporosis effect of RDTF combined with CaCO3." (PMID 34863225, 2021). "In conclusion, the present data indicated that RDTF combined with CaCO3 could effective prevent osteoporosis of ovariectomized rats though acting Wnt3a/β-catenin signal pathway to promote osteogenesis and inhibit osteoclastogenesis." (PMID 34863225, 2021). "Our in vitro studies with four LRP5 mutations causing primary osteoporosis showed that all the LRP5 constructs were able to mediate signaling and that the signaling activity was enhanced several-fold in all the constructs when Wnt3a was added, supporting the role of Wnt3a as a ligand for LRP5." (PMID 22487062, 2012). "NM improved proliferation, ALP activity, mineralization, and expression of osteoblast differentiation markers (BMP-2, p-SMAD 1/5/8, RUNX2, Wnt3a, osteocalcin, and COL-1) in an osteoblastic cell line in vitro and in a model of osteoporosis in vivo." (PMID 32013042, 2020). "In addition, taurine increased the expression levels of BMP-2, Wnt3a, SMAD1/5/8, RUNX2, and COL-1 in the in vivo osteoporosis model and stimulated the p-Akt, p-p38, p-JNK, and p-ERK signaling pathways." (PMID 31970094, 2019). "Furthermore, these Ca extracts increased the expression levels of BMP-2, Wnt3a, SMAD5, RUNX2, osteocalcin and COL-1 in an in vivo model of osteoporosis, while they decreased TRAP, cathepsin K and RANK expression levels." (PMID 28513557, 2017). "Indeed, Wnt3a-mediated signaling stimulates bone formation and inhibits bone resorption in OVX mice, pointing out Wnt3a as a potential therapeutic target for osteoporosis treatment." (PMID 33297501, 2020).